RIPK2 (receptor interacting serine/threonine kinase 2)
Diseases named in the same sentence as RIPK2 in open-access papers (continued):
Sharing a sentence is not in itself a finding about the gene and the disease.
bacterial infection (15 papers, 2015 to 2025). "Several studies have demonstrated increased RIPK2 mRNA expression following bacterial infections, including Legionella pneumophila, Mycobacterium tuberculosis, Listeria monocytogenes, Salmonella enterica, and Chlamydia pneumoniae." (PMID 40406369, 2025). "During certain bacterial infections, RIPK2 oligomerizes in the cytoplasm, forming a helical structure composed of 12 RIPK2-CARD monomers, which is referred to as the “RIPosome”." (PMID 40406369, 2025). "As a member of the RIPKs family, RIPK2 plays a major role in bacterial infections and inflammatory responses." (PMID 35508972, 2022). "Here, we demonstrate that bacterial infection induces the formation of endogenous RIPK2 oligomers (RIPosomes) that are self‐assembling entities that coat the bacteria to induce NF‐κB response." (PMID 36221902, 2022). "We found that upon bacterial infection endogenous RIPK2 undergoes oligomerization to form RIPosomes in macrophages." (PMID 36221902, 2022). "Taken together, these results demonstrate that IRGM suppresses multiple inflammatory responses during bacterial infection and limits the array of RIPK2‐dependent pro‐inflammatory responses." (PMID 36221902, 2022). "Receptor-interacting protein kinase 2 (RIPK2, also known as RIP2) was reported to be associated with bacterial infections as well as inflammatory responses." (PMID 35508972, 2022). "Bacterial infection induces the formation of RIPK2 oligomers that coat the bacteria to enhance NF‐κB response, a process that is counteracted by selective autophagy of RIPK2 oligomers." (PMID 36221902, 2022). "We noticed that XIAP levels also declined upon bacterial infection and that this coincided with RIPK2 upshift, suggesting that XIAP activity and protein abundance negatively regulate RIPosome formation." (PMID 31350258, 2019). "The results showed that NOD1 can identify LPS and activate the NF-κB signal pathway by recruiting RIPK2 and then promoting the expression of inflammatory cytokines to induce the resistance of organism against bacterial infection." (PMID 30013548, 2018). "Studies show that RIPK2-deficient mice exhibit increased IL-18 secretion and heightened inflammatory responses following influenza A virus infection, and secondary bacterial infections trigger RIPK2 expression, potentially driving uncontrolled immune responses." (PMID 40406369, 2025). "Interestingly, during bacterial infection IRGM limited the interferon response in a RIPK2‐dependent manner." (PMID 36221902, 2022). "In order to investigate the miRNAs that may be involved in the regulation of RIPK2 and its signaling pathway after bacterial infection." (PMID 33868233, 2021). "Recently, study in miiuy croaker (Miichthys miiuy) showed that NOD1 can identify LPS and activate the NF-κB signal pathway by recruiting RIPK2 and then promoting the expression of inflammatory cytokines to induce the resistance of organism against bacterial infection." (PMID 30873182, 2019). "By contrast, mutation of Y474 resulted in an RIPK2 protein incapable to induce neither IL-8 nor RIPosomes upon bacterial infection." (PMID 31350258, 2019). "Thus, in-depth study of RIPK2-mediated signaling pathways may help clarify the resistance of fish to bacterial infections." (PMID 33868233, 2021). "Our proposed model emphasizes RIPK2’s dynamic interaction with NOD-like receptors, particularly its transient oligomerization during bacterial infection." (PMID 40406369, 2025). "RIPK2, also known as RIP2, is a protein used by NOD1 and NOD2 to direct the innate immune response against viral and bacterial infections." (PMID 36733771, 2022). "Evidence from overexpression systems suggests that during bacterial infections, the autophagy-related protein ATG16L1 might interact with RIPK2, although this interaction has not been confirmed in studies of IAV infections." (PMID 40406369, 2025).
bacterial infection (continued). "NOD1 and NOD2 receptors also respond to bacterial infections through an alternative pathway, independent of RIPK2 and NF-κB signaling." (PMID 30791886, 2019). "In line with lack of RIPosome formation by RIPK2 Y474F, this protein remained in the soluble fraction upon bacterial infection of the cells." (PMID 31350258, 2019). "However, miRNAs involved in the regulation of RIPK2 and its signaling pathway have not been found in fish during bacterial infection." (PMID 33868233, 2021).
inflammation (3 papers, 2021 to 2022). Aberrant reaction of the microcirculation characterized by movement of fluid and leukocytes from the blood into extravascular tissues. "Consistently, the therapeutic inhibition of RIPK2 ameliorates Shigella infection‐ and DSS‐induced gut inflammation in Irgm1 KO mice." (PMID 36221902, 2022).
cardiovascular diseases (1 paper, 2025). "This suggests that RIPK2 may play an important role in cardiovascular diseases." (PMID 40406369, 2025).
neurological diseases (1 paper, 2025). "Recently, as the NOD1/2-RIPK2 signaling pathway’s neural role is revealed, RIPK2’s key part in neurological diseases enhances its translational value." (PMID 40406369, 2025).
RIPK2 also shares sentences with these, for which no sentence is quoted: squamous cell carcinoma (3 papers); ulcerative colitis (3); bladder urothelial carcinoma (2); cardiac ischemia (2); cerebral artery (2); cognitive deficits (2); diffuse large B-cell lymphoma (2); dyslipidemia (2); head and neck squamous cell carcinoma (2); ileitis (2); kidney clear cell carcinoma (2); lung adenocarcinoma (2); osteosarcoma (2); adenocarcinoma (1); adenoma (1); atherosclerosis (1); autoimmune uveitis (1); bladder neoplasms (1); breast invasive carcinoma (1); cervical squamous cell carcinoma (1); cholangiocarcinoma (1); clear-cell adenocarcinoma of (1); colon adenocarcinoma (1); colorectal adenoma (1); coronary artery disease (1); cystic fibrosis (1); endocervical adenocarcinoma (1); endometrial cancer (1); esophageal carcinoma (1); head and neck cancer (1).
A further 31 diseases each share a sentence with RIPK2 in 1 paper.